IGF1 (insulin like growth factor 1)
Diseases named in the same sentence as IGF1 in open-access papers (continued):
Sharing a sentence is not in itself a finding about the gene and the disease.
cognitive decline (continued). "Therefore, we propose that a low IGF-1 level at baseline might serve as a serum biomarker for cognitive decline in PD patients through further cohort studies." (PMID 26657015, 2015). "Both substances cross the blood-brain barrier and bind to receptors in the central nervous system to stimulate the growth of glial cells, myelination, and neurons: therefore, age-related decreases in serum GH and IGF-1 levels might contribute to cognitive decline in the elderly." (PMID 25713518, 2015). "Contrarily, Royal and Plamen observed that the levels of insulin-like growth factor 1 and IGF-binding protein 2 levels were found to be altered in patients with cognitive decline and physical frailty." (PMID 39201987, 2024). "Moreover, IGF-1 might have a role in the early cognitive decline after adrenalectomy." (PMID 36671407, 2022). "IGF-1 may play a role in the mechanism behind the cognitive benefit of RT and KYN may be a surrogate biomarker for neurodegeneration and cognitive decline." (PMID 38600451, 2024). "Other factors by which physical exercise can interfere beneficially for cognition include the release of growth factors such as BDNF, Insulin-like growth factor 1 (IGF-I), and vascular endothelial growth factor (VEGF), possibly providing reserve against later cognitive decline and dementia." (PMID 33584215, 2020). "Therefore, IGF-1 can modulate various ion channels and molecular signlaing pathways to attenuate inflammation and promote BBB-CP stability to prevent Aβ deposition and cognitive decline in AD." (PMID 36691085, 2023). "The cognitive decline seen on day three after adrenalectomy (despite no significant cell death) could possibly be due to the early (24 h) significant decreases in IGF-1 levels." (PMID 36671407, 2022). "Recent research suggests that systematic exercise could counteract cognitive decline by improving brain blood flow, boosting neuroplasticity through the brain-derived neurotrophic factor (BDNF), and by triggering the release of neurotrophic factors such as insulin-like growth factor (IGF-1)." (PMID 39407758, 2024). "This is also related to the receptor function, where insulin-like growth factor 1 (IGF1) resistance and insulin receptor substrate (IRS) 1 and 2 dysfunctions may be triggered by the A-beta oligomers and hormonal resistance, ultimately leading to notorious cognitive decline." (PMID 33391936, 2021). "Moreover, although the link between IGF-1 levels and age-related diseases is not fully established, it has been demonstrated that increased levels of IGF-1 are associated with tumor development, whereas it might reduce the risk of cognitive decline, dementia and cardiovascular disease." (PMID 33808654, 2021).
Laron syndrome (97 papers, 2006 to 2026). Laron syndrome is a congenital disorder characterized by marked short stature associated with normal or high serum growth hormone (GH) and low serum insulin-like growth factor-1 (IGF-I) levels which fail to rise after exogenous GH administration. "The essential role of IGF-1 in follicular development and homeostasis is illustrated in individuals with Laron syndrome (characterized by congenital IGF-1 deficiency), who exhibit sparse and structurally abnormal hair." (PMID 41020895, 2025). "Crucial role of IGF-1 was discovered inter alia through studies involving deficient patients with short stature, including Laron syndrome individuals." (PMID 36269524, 2023). "Laron syndrome (LS) is a rare genetic disorder characterized by low levels of insulin-like growth factor 1 (IGF1) and high levels of growth hormone (GH) due to mutations in the growth hormone receptor gene (GHR)." (PMID 37189345, 2023). "Laron syndrome is the best described type of IGF1 deficiency under the spectrum of the GH-IGF1 pathologies." (PMID 37941907, 2023). "Epidemiological analyses have shown that patients with Laron syndrome (LS), the best-characterized disease under the umbrella of the congenital IGF1 deficiencies, seem to be protected from cancer." (PMID 37941907, 2023). "Our analyses identified NPNT as the top down-regulated gene in Laron syndrome cells, a condition associated with diminished IGF1 levels." (PMID 36479090, 2022). "TXNIP is highly expressed in lymphoblastoid cells derived from Laron syndrome patients, a type of congenital IGF1 deficiency." (PMID 36479090, 2022). "Evidence for the association of IGF-1 with cancer risk overall is demonstrated by a reduced cancer incidence in Laron Syndrome patients." (PMID 36556357, 2022). "Our previous study on Laron syndrome, a rare congenital IGF1 deficiency, identified a novel link between the IGF1 signaling pathway and TXNIP." (PMID 36291127, 2022). "In Laron syndrome patients, who have congenital IGF1 deficiency, the administration of IGF1 restores sexual maturation." (PMID 35459135, 2022). "Recent genomic analyses of Laron syndrome (LS) patients, a type of dwarfism under the spectrum of the congenital IGF1 deficiencies, allowed us to identify ZYG11A as a new downstream target for IGF1 action." (PMID 34220714, 2021). "In this context, Laron syndrome, characterized by a loss of function mutation in the growth hormone receptor gene, leading to high levels of GH combined with low levels of IGF-1, is particularly instructive." (PMID 34948002, 2021). "Laron syndrome has also been associated with hearing impairment, and the only treatment available thus far is recombinant human IGF-1 (rhIGF-1) therapy." (PMID 34680948, 2021). "Delayed puberty is a common finding in children with GH deficiency (GHD) or patients with Laron syndrome, a genetic form of GH resistance with undetectable or very low IGF1 levels." (PMID 33671044, 2021). "Laron syndrome (LS) is the best characterized entity under the spectrum of the congenital IGF1 deficiencies." (PMID 34204736, 2021). "rhIGF-1 has been approved as an orphan drug for the treatment of growth failure in children and adolescents with severe primary IGF-1 deficiency including Laron syndrome." (PMID 34680948, 2021). "The best-known condition of IGF-1 deficiency is Laron syndrome (also known as Laron dwarfism or GHI), predominantly found in children, characterized by alterations in growth hormone receptors (GHR) in the liver, and hence, reducing IGF-1 synthesis." (PMID 32046737, 2020). "This has been shown most clearly by the almost complete protection from cancer in patients with Laron dwarfism, who have very low levels of serum IGF-1 due to GH receptor mutation." (PMID 31416218, 2019). "Laron syndrome (LS), or primary growth hormone resistance, is a prototypical congenital insulin-like growth factor 1 (IGF1) deficiency." (PMID 31208077, 2019).
Laron syndrome (continued). "Studies of patients with Laron syndrome demonstrate this phenomenon; long-term treatment with recombinant IGF-1 is associated with an increase in adiposity." (PMID 28947559, 2017). "The primary condition of IGF-1 deficiency in humans is Laron Syndrome, characterized by low body weight and stature, similar to the one found in mice." (PMID 26467524, 2015). "The potential role of IGF-1 in the regulation of human erythropoiesis has also been confirmed by studies performed in patients with Laron syndrome (primary IGF-1 deficiency), where the infusion of IGF-1 significantly raises the red blood cell parameters." (PMID 26779261, 2015). "Replacement therapy using recombinant IGF-1 rescues patients from the hearing loss in Laron syndrome." (PMID 25309440, 2014). "Pituitary growth hormone (GH) is a major modulator of IGF1 levels, and individuals with congenital GH deficiency (e.g. Laron syndrome) or hypopituitarism are growth-retarded in the third trimester with reduced IGF1 at birth." (PMID 24034272, 2014). "In contrast, short stature is a characteristic feature of congenital IGF-1 deficiency in Laron syndrome." (PMID 21699736, 2011). "Laron syndrome is associated with IGF-1 deficiency and mutations in growth hormone (GH) receptor." (PMID 36269524, 2023). "Interestingly, inactivating mutations in the GH receptor in humans result in Laron syndrome (LS), a clinical entity characterized by increased serum levels of GH and decreased insulin growth factor-1 (IGF-1)." (PMID 37163287, 2023). "The known clinical hair phenotype associated with Laron syndrome or reduced GH serum levels, which is also associated with decreased expression of IGF-1, would have led one to expect that the growth of organ-cultured human scalp HFs would be promoted by GH treatment." (PMID 34948002, 2021). "Laron syndrome (LS) is a rare inherited disorder characterized by severe postnatal growth failure, normal or increased circulating growth hormone (GH) secretion and insulin-like growth factor 1 (IGF-1) deficiency." (PMID 33912130, 2021). "The variations of cortical thickness in the cingulate cortex and frontal lobe are consistent with previous reports from young patients with GH receptor deficiency, since IGF-1 signaling is supposed to play an important role in brain regeneration in these areas." (PMID 31695595, 2019). "Apparently, IGF-1 does not appear to bemandatory for ovulation and conception since Laron-type dwarfism patients, whichhave normal GH levels and a complete inability to generate IGF-1, are capable ofovulation and conception." (PMID 40080785, 2025). "In a study of seven patients with Laron syndrome (GH resistance), administration of IGF-1 for five years led to a decrease in platelet count." (PMID 38566781, 2024). "For example, Laron’s syndrome, an autosomal recessive genetic disorder characterized by GH insensitivity, results in abnormally low IGF-1 levels in the bloodstream." (PMID 39050250, 2024). "Additionally, IGF-1 signaling may impact the human epidermis, as patients with conditions involving hyposecretion, such as Laron syndrome (characterized by primary IGF-1 deficiency and growth hormone resistance), are not only short in stature but also exhibit early aging phenotypes like wrinkles." (PMID 39638246, 2024). "While IGF-1 is clinically approved to be used in IGF-1 deficiency, most prominently Laron's dwarfism, other clinical trials with encouraging results have not progressed to clinical application." (PMID 39638246, 2024). "To date, the only drug in the market for RTT is Trofinetide which is based on IGF-1 a growth factor previously used for diseases such as Laron syndrome and liver cirrhosis." (PMID 39384967, 2024). "Pathological conditions like dwarfism, including Laron syndrome with substantially low levels of IGF-1, allowed us to discover crucial role of that protein in growth and maturation reduction." (PMID 36269524, 2023).
Laron syndrome (continued). "Laron syndrome (LS) is a rare inherited disorder characterized by low circulating insulin-like growth factor 1 (IGF1) and high circulating growth hormone (GH) due to mutations in the growth hormone receptor gene (GHR)." (PMID 37189345, 2023). "IGF-1 levels in patients with Laron syndrome are very low and protected them from cancer, as is the case in animal models with low IGF-1." (PMID 36235844, 2022). "Laron syndrome (LS) is a genetic disorder that results from the mutation or deletion of the growth hormone receptor (GHR) gene, thereby leading to impaired IGF1 production and dwarfism." (PMID 36291127, 2022). "Low levels of IGF-1 have been correlated with reduced ocular axial length in Laron’s syndrome patients with IGF-1 supplementation reducing the disparity to normal levels." (PMID 35053340, 2022). "The only treatment tested for growth hormone receptor (GHR) defective Laron Syndrome (LS) is injections of recombinant insulin-like-growth factor 1 (rhIGF1)." (PMID 35105948, 2022). "Laron syndrome patients have similar phenotype to Sec23bki/ko mice in growth restriction, increased GH, and decreased serum IGF-1 levels." (PMID 34954140, 2022). "The only treatment for patients with Laron Syndrome is recombinant IGF-1, which restores much of their growth deficits." (PMID 36556357, 2022). "Laron syndrome (LS) is an inherited autosomal recessive disorder caused by molecular defects of the GH receptor (GHR) gene, leading to congenital IGF1 deficiency." (PMID 36291127, 2022). "Laron syndrome (LS) is a type of dwarfism that results from the mutation of the growth hormone receptor (GHR) gene, leading to congenital IGF1 deficiency." (PMID 34204736, 2021). "The Laron syndrome constitutes the best characterized entity under the umbrella of the IGF1 pathologies." (PMID 34769292, 2021). "Compared with untreated patients with Laron syndrome (LS), susceptibility to mild myopia has been observed in patients with LS (OMIM 262500) who received treatment with IGF-1." (PMID 21976954, 2011). "Similarly, mice with a GHR deletion (Ghr−/−), which models Laron syndrome (characterized by low levels of IGF-1), exhibit increased longevity and metabolic benefits." (PMID 40260058, 2025). "IGF-1 is the sole effective therapeutic intervention for Laron’s syndrome." (PMID 39050250, 2024). "Growth hormone receptor deficiency (GHRD) in humans is brought on by GHR mutations that result in low levels of both insulin and insulin-like growth factor 1 (IGF-1); as a result, the circulating levels of IGF-1 affect brain structure and function during development and aging." (PMID 37762211, 2023). "Knockout mice for Ghr are Laron syndrome models and exhibit retarded postnatal growth, dwarfism, decreased plasma IGF-1 levels and small pituitary glands, the auditory phenotype of these animals has not been studied despite the fact that studies with patients show a predisposition to suffer SNHL." (PMID 34680948, 2021). "The role of GH/IGF-1 axis activity on longevity and aging-related diseases in human is also supported by long-term studies of an Ecuadorian cohort affected by Laron syndrome (LS) which is characterized by GHR deficiency and consequently is responsible for a 90% reduction of the IGF-1 levels." (PMID 34572814, 2021). "Laron syndrome (LS) is a rare autosomal recessive growth retardation from a mutation in the growth hormone receptor (GHR) gene leading to defective GHR, growth hormone insensitivity and eventual low levels of insulin-like growth factor type 1 (IGF-1)." (PMID 32296486, 2020). "Laron syndrome (LS) is a genetic type of dwarfism that results from mutation of the growth hormone receptor (GHR) gene, and is the best characterized entity under the spectrum of the congenital IGF1 deficiencies." (PMID 31320996, 2019).
Laron syndrome (continued). "Primary growth hormone insensitivity (Laron syndrome) is the most common and prototypical condition within the primary IGF deficiency (PIGFD) category, which is characterized by extremely low serum IGF-1 levels that may require IGF-1 treatment." (PMID 30018981, 2018). "Mutations in GHR cause Laron syndrome, a rare disease (ORPHA:633) characterized by marked short stature, low serum IGF-1 levels and auditory defects like late onset SNHL, auditory hypersensitivity and lack of acoustic stapedial reflexes, which may be prevented by IGF-1 treatment." (PMID 34680948, 2021). "Of note, IGF-1 may also act as a co-gonadotropin at the ovary, and reversible PCOS may develop in women with Laron’s syndrome treated with recombinant IGF-1." (PMID 40747135, 2025). "However, non-GH deficient short stature disorders, such as idiopathic short stature (ISS) and growth hormone insensitivity (GHI), often present with normal GH when accompanied by lower serum IGF-1 levels." (PMID 35204932, 2022). "Patients with Laron syndrome, caused by loss-of-function mutations in the GH receptor gene in humans, develop NAFLD and chronic replacement of insulin-like growth factor 1 (IGF-1) does not alleviate NAFLD status." (PMID 36699040, 2022). "Moreover, the growth hormone (GH)/insulin-like growth factor 1 (IGF1) system may be involved in the function of gonadotropin-releasing hormone (GnRH) neurons, as delayed puberty is commonly found in patients with GH deficiency (GHD) or with Laron syndrome, a genetic form of GH resistance." (PMID 33671044, 2021). "It has not been extensively investigated in growth hormone insensitivity (GHI; short stature, IGF-1 deficiency and normal/high GH) or previously in IGF-1 insensitivity (short stature, high/normal GH and IGF-1)." (PMID 33055295, 2020). "Without GH, IGF1 is not secreted at sufficiently high levels, so IGF1 treatment in human patients can reverse the micro-penis seen in Laron syndrome." (PMID 31963388, 2020). "Patients with Laron syndrome treated with IGF-1 demonstrated lower growth rates compared to patients with GHD treated with daily GH, supporting the contribution to growth that both GH and IGF-1 provide." (PMID 28947559, 2017). "IGF‐1 was half the expected with very low GH basal levels and no response to clonidine stimulation, a common finding in never‐treated adult patients with Laron Syndrome." (PMID 29152285, 2017). "Since recombinant IGF-1 has been synthesized, it has been used clinically in replacement therapy in patients with primary growth hormone-resistance (Laron syndrome) where IGF-1 is not synthesized." (PMID 25309440, 2014). "Thus, Western diet shifts the GH/IGF-1 axis to abnormally high levels, just in the opposite direction of low IIS observed in Laron syndrome." (PMID 21699736, 2011). "In contrast, in four out of six women with primary growth hormone resistance (Laron syndrome), chronic treatment (many months) with excessive doses (120–150 micrograms/kg/day) of recombinant human IGF-1, resulted in hyperandrogenism, perhaps reflecting a supraphysiological dose of IGF-I." (PMID 35269778, 2022). "Notably, individuals with Laron syndrome also exhibit an almost complete absence of cancer, further suggesting that reduced IGF-1 signaling may confer protective effects against both neurodegeneration and tumorigenesis." (PMID 40260058, 2025).